VHL (von Hippel-Lindau tumor suppressor)
Diseases named in the same sentence as VHL in open-access papers (continued):
Sharing a sentence is not in itself a finding about the gene and the disease.
tumor (continued). "In approximately 90% of cases, this metabolic reprogramming in ccRCC is often related to von Hippel-Lindau (VHL) tumor-suppressor mutations; in VHL-deficient ccRCC, HIF1α increases the expression of GLUT-1, which then promotes cellular glucose uptake." (PMID 35671305, 2022). "VHL loss leads to the stabilization of hypoxia-inducible factor α (HIFα) and other substrate proteins, which, together, drive various tumor-promoting pathways." (PMID 35159281, 2022). "A bioinformatic analysis revealed that RSUME expression is increased in RCC tumors bearing VHL mutated form and it rises from earlier to late tumor stages during RCC progression." (PMID 35528020, 2022). "Mutations of the von Hippel-Lindau (VHL) tumor suppressor gene have been observed in approximately 80% of KIRC tumors, which is one of the important factors driving the occurrence and development of KIRC." (PMID 35121728, 2022). "In renal clear cell carcinoma, loss of Von Hippel-Lindau (VHL) tumor suppressor function that leads to a significant increase in HIF activity is a critical indicator." (PMID 35794625, 2022). "In fact, ~70% of sporadic RCC lesions show VHL mutations but with a higher degree of tumor heterogeneity due to additional lost tumor suppressor genes on chromosome 3p." (PMID 36421797, 2022). "According to the results of tumor mutational burden analysis, VHL and PBRM1 made up the majority of the mutations." (PMID 36035192, 2022). "Loss of pVHL confers fitness disadvantage in most cell types examined to date, which likely contributes to the narrow range of tumor types linked to VHL mutations." (PMID 36106637, 2022). "VHL loss of function also causes the hyperactivation of mTOR, which correlates with tumor progression and poor outcomes in ccRCC patients." (PMID 35892875, 2022). "While it was not statistically significant, we did observe a potential association between VHL mutations and tumour stage and size." (PMID 35444164, 2022). "The first hit, germline mutation in the VHL gene, leads to the inactivation of a tumor suppressor allele." (PMID 36556926, 2022). "Tumors with VHL mutations were associated with a well-defined tumor margin; nodular enhancement; and presence of intratumoral vascularity." (PMID 35159060, 2022). "It has been shown that the endothelium of VHL patients is functionally compromised and more susceptible to tumor development." (PMID 35205407, 2022). "ccRCC represents 75% of all RCC cases, and about 80% of ccRCC cases harbor mutations of the tumour-suppressive gene, VHL." (PMID 35461314, 2022). "This protocol customizes the evaluation of germline VHL variants in disease using informative somatic tumor data." (PMID 35774415, 2022). "Regarding tumor heterogeneity, genomic analyses of multi-region tumor samples from mRCC patients showed that VHL mutation and loss of one copy of 3p were ubiquitous in all analyzed regions and tumors." (PMID 34575959, 2021). "Recently, small molecules that directly inhibit HIF-2α were shown to cause tumor regression in preclinical models of primary and metastatic VHL-defective ccRCC." (PMID 33540838, 2021). "ccRCC is one of the most highly vascular tumor type, which is driven by intensive release of vascularization factors in response to VHL mutation and hypoxia pathway activation." (PMID 34638458, 2021). "Pax2 downregulation has been shown to lead to growth inhibition of cancer cells, and reactivation of Pax2 is also observed in clear cell renal cell carcinoma, a tumor type characterized by loss of VHL tumor suppressor function." (PMID 34195082, 2021). "Von Hippel Lindau (VHL) gene locates in chromosome 3p25-p26 and encodes VHL proteins, among which pVHL19 and pVHL30 are tumor-suppressing proteins and defined as pVHL." (PMID 34923986, 2021). "Von Hippel–Lindau (VHL) disease is characterized by frequent mutation of VHL protein, a tumor suppressor that functions as the substrate recognition subunit of a Cullin2 RING E3 ligase complex (CRL2VHL)." (PMID 34174286, 2021).
tumor (continued). "Another example is Von Hippel–Lindau, an autosomal dominant disease caused by mutations in the VHL gene, a tumor suppressor gene." (PMID 34204582, 2021). "Abnormal hypoxia inducible factor (HIF) expression caused by VHL gene deletion has been shown to promote tumor angiogenesis, glycolysis, and metastasis." (PMID 34774030, 2021). "We re-introduced a retrovirus encoding full length VHL cDNA (VHL30) and observed downregulation of RAPTOR protein abundance as compared with VHL-deficient 786-O tumor cells." (PMID 34290272, 2021). "VHL is a tumor suppressor gene encoding for two isoforms of VHL protein (pVHL), both playing an important role in regulating the hypoxia response in all cell types, being considered of great importance in maintaining cell homeostasis." (PMID 34571962, 2021). "The most well characterized is increased expression of glycolytic genes that results from loss/mutation of VHL, a common tumor initiating event." (PMID 34609963, 2021). "Gene mutation and tumor mutation burden analyses indicated somatic pathogenic mutation of VHL gene (c.500G > A, p.Arg167Gln)." (PMID 34923986, 2021). "This patient underwent a nephrectomy for a clear cell RCC and tumor only sequencing revealed a likely germline MITF p.E318K alteration (variant allele frequency (VAF): 52%) with a likely somatic alteration of VHL (VAF: 10%)." (PMID 34767027, 2021). "Genes or proteins whose expressions are associated with lower tumor fitness and, consequently, better cancer patient survival in the context of VHL inactivation would theoretically be ideal targets for treating ccRCC." (PMID 34135317, 2021). "Each tumor has different additional somatic mutations, an indication that after common loss of VHL there are different evolutionary trajectories during tumor progression." (PMID 33803184, 2021). "CCRC is frequently characterized by the inactivation or mutation of the VHL gene, a tumor suppressor gene, leading to angiogenesis through the transcription of potent pro-angiogenic factors regulated by HIF, such as VEGF." (PMID 34885006, 2021). "All our tumor samples will also be examined for somatic mutations since these are also detected in 30% of sporadic HNPGLs, mainly involving VHL, NF1, RET and HIF2α genes, although these are rarely associated with multiple HNPGLs." (PMID 34072806, 2021). "Methylation of the promotor region of the tumor suppressor genes, for instance VHL, was associated with angiogenesis, leading to an enhanced supply for the tumor environment." (PMID 33401659, 2021). "On the basis of global gene expression profiling, our data demonstrate that the R167Q VHL mutation leads to molecular changes indicative of more pronounced stem cell traits and that the mutation is a presumed source of tumor heterogeneity and resistance." (PMID 34359798, 2021). "NF-κBp 65, NF-κBp50, VEGF, HIF-2; VHL elevated mRNA level by 10.6; 13.5; 240.6; 11.5; 368.5 times found in tumors with mutation, respectively, compared to the primary tumor with the wild variant of the BRAF gene." (PMID 34319022, 2021). "By Kaplan–Meier analysis, it was estimated that there was a 5% risk of developing a VHL-type tumour after 10 years of follow-up." (PMID 34573396, 2021). "In particular, the crucial role of the mutation of the von Hippel–Lindau (VHL) tumor suppressor gene, leading to angiogenesis through the transcription of multiple pro-angiogenic factors, is clearly recognized." (PMID 34885006, 2021). "Von Hippel–Lindau (VHL) disease is a rare hereditary cancer syndrome caused by germinal mutations of the VHL tumor suppressor gene." (PMID 34359798, 2021). "Increased tumor immunogenicity during tumor progression is the foremost progression step associated with VHL inactivation." (PMID 34563045, 2021). "Von Hippel–Lindau disease (VHL) is a rare hereditary syndrome due to mutations of the VHL tumor suppressor gene." (PMID 34359798, 2021).
tumor (continued). "In patients with VHL-associated tumour presentations, the most frequent detection of pathogenic variants in the VHL gene is the result of directed genetic testing or inherited cancer gene panels." (PMID 33654607, 2021). "This happens because tumor-driven VHL mutation leads to the activation of the HIF1/2α pathway and downstream pathway permutation." (PMID 34638458, 2021). "The mutations in VHL are known to occur early in tumour development, which is in line with our observation that in 39 of 48 (81%) cases, the VHL mutations were shared between both tumour biopsies of a patient." (PMID 33946379, 2021). "Loss of VHL gene in ccRCC, tumor is under pseudohypoxia state with accumulated HIF-2α and activated HIF-1 to upregulate the expression of hypoxia-inducible genes and increase tumor oxygenation." (PMID 34194463, 2021). "In the >80% of ccRCC tumors that harbor somatic VHL mutations, the resulting derangement of HIFα metabolism would be expected to result in a tumor microenvironment consistent with extreme hypoxic conditions." (PMID 34359645, 2021). "Gene mutation and tumor mutation burden analyses indicated germline pathogenic mutation of VHL gene (c.500G > A, p.Arg167Gln)." (PMID 34923986, 2021). "VHL gene mutations but also hypermethylation of the VHL promoter contribute to attenuating its tumor suppressor mechanisms." (PMID 33968761, 2021). "The most common mutation is found on the von Hippel–Lindau (VHL) gene, a tumor suppressor gene that has a key role in angiogenesis." (PMID 34885006, 2021). "Loss of VHL in OC stabilizes HIF-1α which in turn stimulates miR-210 expression inducing tumor aggressiveness." (PMID 35145899, 2021). "The risk of developing a potential VHL-related tumour (haemangioblastoma or RCC) was estimated at 10.8% at 10 years follow-up." (PMID 34573396, 2021). "Factors including solid tumors, smaller tumors, VHL-related lesions, and a greater marginal dose were found to be associated with better tumor control." (PMID 32356022, 2021). "A study analyzing 86 unselected PGL/PCC tumor samples reported that two pathogenic variants were detected in VHL gene." (PMID 33777662, 2021). "This carcinoma is usually associated with inactivation of the von Hippel-Lindau (VHL) tumor-suppressor gene, which causes hypoxia inducible factors (HIF) activation." (PMID 34931765, 2021). "It was also shown that suppression of the mTOR inhibitor DEPTOR in VHL-deficient ccRCC accelerated tumor cell proliferation." (PMID 34290272, 2021). "The loss of the VHL tumor suppressor drives the hypoxic pathway by hypoxia-inducible factors (HIF) transcription factors." (PMID 33923219, 2021). "In this context HIF1α can repress tumor cell proliferation in different biological settings, including that of ccRCC, while HIF2α favors the proliferation of VHL-deficient RCCs and tumor formation." (PMID 33321829, 2020). "The disease is caused by germline mutations in VHL, a tumor-suppressor gene located on chromosome 3p25.1." (PMID 33142830, 2020). "For VHL patients, tumor burden at diagnosis and young age seem to be the most important risk factors for new tumor development." (PMID 32507909, 2020). "Mutations in the von Hippel-Lindau (VHL) tumour suppressor have been reported in approximately 80% of ccRCC and identified as one of the genetic determinants driving ccRCC initiation and progression." (PMID 33372609, 2020). "In humans, inactivation of the von Hippel–Lindau (VHL) tumor suppressor gene predisposes humans to develop highly vascularized neoplasms." (PMID 32610682, 2020). "VHL disease is an autosomal dominantly inherited familial neoplastic condition with an incidence of approximately 1/30,000–1/36,000 live births and is caused by constitutional mutations at the level of the VHL tumor suppressor gene." (PMID 32751108, 2020).
tumor (continued). "The lower percentage of VHL mutations in the different tumor types with complete data sets for all 3 exons was regarded as the more “objective” real mutation rate as compared to the results of only 1–2 interpretable exons." (PMID 32076485, 2020). "Mutation of VHL tumor suppressor is frequently observed in ccRCC patients and identified as a causal event for tumor evolution." (PMID 32513235, 2020). "After surgery, genetic analysis of the tumor tissue showed loss of heterozygosity at the VHL gene locus." (PMID 31673890, 2020). "The correlation tries to subgroup truncating mutations and missense mutations, predicting tumor penetrance and survival of VHL patients." (PMID 33362845, 2020). "One of the landmark events in its tumorigenesis is loss of the short arm of chromosome 3p on which the VHL tumor suppressor is encoded." (PMID 33194717, 2020). "Another example are the mutations inactivating the tumor-suppressing gene VHL, that correlate with a higher rate of angiogenesis and tumor cell survival in renal cancer." (PMID 32707662, 2020). "The most common (75%) histological subtype is clear cell RCC (conventional) (ccRCC), which are characterised by loss of the VHL tumour-suppressor gene, followed by papillary (10–15%) and chromophobe (5%) RCC." (PMID 32390008, 2020). "Biallelic loss of VHL gene function through somatic loss of the second allele results in a state of pseudo hypoxia in cells that leads to angiogenesis and tumor or cyst formation." (PMID 31673890, 2020). "TGFα binds to the EGFR receptor and is a potent angiogenic factor, forming an autocrine or juxtacrine loop to promote tumor progression in VHL-associated renal cell carcinoma." (PMID 32432044, 2020). "Using an NGS sequencing panel of 68 cancer‐related genes tumor sequencing was performed on the two renal tumors to assess VHL mutation state." (PMID 31943436, 2020). "Well-defined tumor margins, nodular tumor enhancement, and intratumoral vascularization were associated with VHL mutations, while renal vein invasion was significantly associated with KDM5C and BAP1 mutations." (PMID 31901171, 2020). "The loss of the von Hippel-Lindau tumour suppressor gene (VHL) in these tumours favours stabilization of the Hypoxia Inducible Factors (HIF), which in turn contribute to adapt tumour cells to hostile environments promoting tumour progression." (PMID 31980715, 2020). "In recent studies, researchers have considered the tumor burden of VHL-associated HGBs to be associated with partial germline mutations, male sex and a younger age." (PMID 33110457, 2020). "ccRCC, the dominant histologic subtype of RCC, is closely associated with mutation or inactivation of the von Hippel-Lindau (VHL), tumor suppressor gene that encodes VHL protein which is a key component of the cellular oxygen-sensing pathway." (PMID 32850419, 2020). "We observed that miR-212/132 is upregulated in response to VHL mutation both in zebrafish model systems and in human patient ccRCC tumor material carrying biallelic inactivating VHL mutations." (PMID 32325871, 2020). "The tumorigenic activities of hnRNPA2B1 in VHL-deficient cells were also disclosed with stimulatory effects on cell proliferation, migration, invasion and xenograft tumor growth in our results, which was previously proposed by several investigations." (PMID 32826868, 2020). "Somatic mutation or inactivation via gene modification of both VHL tumor suppressor alleles is commonly observed in ccRCC." (PMID 32260198, 2020). "Regarding other less frequent tumor entities – including tumors introduced or modified by the latest WHO classification of tumors of the Urological Tract – data on VHL mutation and deletion status are also rare." (PMID 32076485, 2020). "VHL is an autosomal dominant syndrome associated with germline mutation in the VHL tumour suppresser gene located on chromosome 3p." (PMID 32631354, 2020).
tumor (continued). "There have been several studies focusing on genotype-phenotype correlations of VHL disease, providing some valuable tumor risk stratification methods mainly based on mutation types or locations of VHL gene." (PMID 33362845, 2020). "This indicates variations in tumor microenvironment caused by VHL that lead to changes in ccRCC macrophage polarization, providing us with useful information to explore new checkpoints." (PMID 33665156, 2020). "The von Hippel-Lindau (VHL) tumor suppressor gene located on chromosome 3p25.3 encodes a multifunctional protein." (PMID 32076485, 2020). "In agreement with our previous qPCR results, we observed widespread overexpression of miR-132 in tumor material from ccRCC samples with biallelic VHL mutations proven by sequencing." (PMID 32325871, 2020). "Glutamine is transformed into glutamate which is subsequently catalyzed into 2-oxo-glutarate (2-OG), and further into lipid via glutaminase enzymatic function in VHL-loss tumor cells." (PMID 33109235, 2020). "It is notable that, in patients with clear cell RCC with mutations in the VHL (von Hippel-Lindau disease tumor suppressor) gene, primary cilia have been lost, and the re-expression of VHL proteins restored cilia expression." (PMID 33339422, 2020). "Von Hippel-Lindau (VHL) genetic syndrome is an autosomal dominant genetic disease caused by pathogenic variants in the VHL tumor suppressor gene on chromosome 3 (3p25–26)." (PMID 33110457, 2020). "Anti-tumor therapy, in addition to established anti-angiogenic therapy, targeting VHL loss and BET inhibition, also has the sustainable treatment based on the potential crosstalk between HIFs and ferroptosis, and targeting CAFs." (PMID 33109235, 2020). "In agreement, 1-13C-glutamine studies in VHL-deficient ccRCC tumour xenografts confirm that glutamine is a significant anaplerotic nutrient." (PMID 32450839, 2020). "Hypoxia or von Hippel-Lindau (VHL) tumor suppressor loss leads to the stabilization of hypoxia-inducible factors alpha (HIF-1α and HIF-2α) and the activation of their signaling to mediate adaptive responses." (PMID 32733884, 2020). "In humans, mutations in the pVHL protein, a tumor suppressor protein, predispose patients to Von Hippel Lindau (VHL) disease, a rare form of dominantly inherited cancer syndrome." (PMID 32284789, 2020). "Von Hippel–Lindau (VHL) disease is an autosomal dominant genetic disease resulting from germline mutations in the VHL tumor suppressor gene on chromosome 3 (3p25–26) within a 10 kb region." (PMID 33004005, 2020). "On the other hand, VHL-deficient cytotoxic T cells are more effective in preventing tumor growth with their enhanced cytotoxicity." (PMID 30413999, 2019). "Based on the best multivariate model, a prognostic nomogram was developed to predict the probabilities of 1-, 3-, and 5-year OS in KIRC using our defined risk group, tumor stage, age, and mutation status of VHL as variables." (PMID 31739630, 2019). "The VHL gene variants were confirmed in both the tumor tissues and blood samples from all patients who were clinically diagnosed with VHL disease." (PMID 31317677, 2019). "A best multivariate model that included our recorded risk group, tumor stage, age, and mutation status of VHL was obtained by a multivariate stepwise analysis." (PMID 31739630, 2019). "Because ccRCC is a highly vascular tumour, attributed to frequent loss of VHL function and subsequent activation of Hypoxia-Inducible Factor (HIF), we stratified the samples by observed activation of the HIF-pathway." (PMID 30792476, 2019). "RSUME levels are higher in tumor patients with VHL mutations and associated with poor prognosis in RCC tumors." (PMID 30890701, 2019). "We investigated the effect of mutations affecting the pVHL tumor suppressor and their correlation with different phenotypes described for VHL patients." (PMID 30943211, 2019).